PLK1 (polo like kinase 1)
Diseases named in the same sentence as PLK1 in open-access papers (continued):
Sharing a sentence is not in itself a finding about the gene and the disease.
cancer (continued). "Inhibition of PLK1 by PLK1 inhibitors or depletion of PLK1 by siRNA-mediated knockdown induced apoptosis and mitotic catastrophe in various cancers, including NB." (PMID 35631350, 2022). "PLK1 is overexpressed in many cancers and serves as a well-validated target for new drugs in pre-clinical and clinical studies." (PMID 35454120, 2022). "Accumulating evidences exemplify the importance of Rho effectors in multi-steps of cancer progression, and PLK1 is one of them." (PMID 36476988, 2022). "PLK1 mRNA expression is reported to be high in actively dividing cells and various cancer cells, including NB." (PMID 35631350, 2022). "The pan-cancer analysis also showed statistic correlation between PLK1 expression level and the prognosis." (PMID 36618405, 2022). "BI 2536 is a selective PLK1 inhibitor promoting mitotic arrest and apoptosis in a variety of cancer cells." (PMID 36054794, 2022). "Some of cell cycle pathways were also associated with a downregulation of polo-like kinases PLK1 and PLK2; the roles of these in cancer is quite controversial where findings suggest both oncogenic and tumor suppressor roles in various cancers." (PMID 35600164, 2022). "From a screening in more than 30 different cancers, a correlation was seen between high levels of PLK1 and inhibition of immune cell infiltration and antitumor immunity." (PMID 35719948, 2022). "The potential of PLK1 inhibition as a therapeutic strategy has been well studied in various cancer types; however, the interplay of PLK1 inhibition with cancer immunity remains mostly unexplored." (PMID 35871223, 2022). "Numerous studies have demonstrated that PLK1 is overexpressed in many cancers correlating with poor prognosis, making PLK1 as a promising target for cancer treatment." (PMID 35844795, 2022). "LHNPs were able to efficiently deliver CRISPR/Cas9 for effective cancer therapy in a mouse flank tumour model by using polo-like kinase 1 (PLK1) as a model gene." (PMID 35999629, 2022). "In this study, we report that PLK1 inhibition results in increased PD-L1 expression in cancer cells." (PMID 35871223, 2022). "In human cancers, there is growing evidence coupling PLK1 activity to tumor development, progression, and therapy resistance." (PMID 34759346, 2022). "Pharmacological PLK1 inhibition in cancer has been successful in reducing tumor volume and promoting decreased viability, cell-cycle arrest, and eventually apoptosis." (PMID 34561554, 2022). "We investigated the expression characteristics of the PLK1 protein in 41 different normal tissues and various cancers using the HPA database, respectively." (PMID 36618405, 2022). "Excision repair cross-complementation group 6 like (ERCC6L), a polo-like kinase 1 (PLK1)-interacting checkpoint helicase, confers a high risk of cancer and enhances the progression of a variety of cancers." (PMID 36550435, 2022). "Elevated levels of PLK1 are also observed in different cancers, including NB, breast, colorectal, melanoma, prostate, ovarian, esophageal, and non-small-cell lung cancer." (PMID 35631350, 2022). "PLK1 inhibitors have now been tested clinically and found to be beneficial in the treatment of individuals with cancer." (PMID 35256538, 2022). "Previous studies have confirmed that by inhibiting cSCC keratinocyte PLK1 signaling in vitro, the cancer cells die first, emphasizing the indispensability of the PLK1 signaling pathway in the development of cSCC." (PMID 36247089, 2022). "The PLK1 pathway has previously been shown in a large number of studies to be closely related to a variety of cancers, including BRCA, and plays a role in multiple biological processes such as BRCA cell proliferation, drug resistance, and metastasis." (PMID 36568373, 2022). "To further learn the PLK1 mRNA expression condition in different cancers, we tested the PLK1 mRNA expression across the RNA-seq data of a variety of malignancies in TCGA." (PMID 36618405, 2022).
cancer (continued). "Our study provides evidence for the relationship between PLK1 inhibition and cancer immunosuppression, and supports the combination of PLK1 inhibitor and PD-L1 immune checkpoint blockade as a potential therapeutic option." (PMID 35871223, 2022). "Overexpression of the PLK1 gene has been found in many different types of tumors and is related to the poor prognosis of cancers." (PMID 36605099, 2022). "Since amino acid metabolism is linked to the cell cycle, targeting the serine/threonine-protein kinase PLK1 as a cell cycle regulator has been proven a viable therapeutic strategy against cancer chemoresistance." (PMID 35910374, 2022). "Tozasertib is a pan-Aurora inhibitor, mostly against Aurora A. Volasertib is an experimental small-molecule inhibitor of the PLK1 (polo-like kinase 1) protein and is developed for use as an anti-cancer agent." (PMID 36104333, 2022). "We and others have previously reported that PLK1 inhibition or knockdown results in a cell cycle arrest in G2/M phase leading to cancer cell death." (PMID 35871223, 2022). "Based on these reports, the PLK1 expression level is a useful prognostic marker in several carcinomas." (PMID 35379935, 2022). "Silencing PLK1 expression via siRNAs can inhibit the cell cycle progression and initiates the apoptosis of cancer cells, holding significant promise for cancer therapy." (PMID 34006888, 2021). "Overexpression of CDK1, MCM2, E2F2, PLK1, CCNB1/2, BUB1, BUB1B, CDC25 has been associated with aberrant proliferation in many cancer types including HCC." (PMID 33499054, 2021). "Volasertib (BI 6727), by Boehringer Ingelheim, is a dihydropteridinone-derived, ATP-competitive kinase inhibitor of PLK1, active in preclinical studies on various cancers and is being tested as anticancer agent in many clinical trials." (PMID 34885651, 2021). "Here we demonstrated that the Polo-like kinase 1 (PLK1) inhibitor volasertib, which has been employed in cancer clinical trials, has activity against GBM in the contexts of both as monotherapy and as an adjunct to standard of care (SOC)." (PMID 34680264, 2021). "Given that those inhibitors reduce the cancer cell viability, PLK1 and Aurora kinases are prominent targets for new anticancer drugs." (PMID 33465289, 2021). "In another study, it was reported that RO3280 (a PLK1 inhibitor) restrained the proliferation of cancer cells by inducing cell cycle arrest at the G2/M point." (PMID 34565365, 2021). "Since PLK1 is involved in the regulation of mitotic exit and cytokinesis, PLK1 expression has been found with a high level in various cancers." (PMID 34080290, 2021). "Here, we uncover a hypoxia-regulated mechanism of Plk1-mediated cancer metastasis and drug resistance." (PMID 33547392, 2021). "The link between two major cancer hallmarks, cell proliferation through activation of Plk1 and hypoxia through HIF-α stabilization, constitute an important mechanistic part of the present study." (PMID 33547392, 2021). "Polo-like kinase 1 (PLK1) is overexpressed in a multitude of human cancers, and inhibition of PLK1 can induce mitotic arrest and apoptosis, indicating utility for siRNA to silence PLK1." (PMID 34727233, 2021). "PLK1 is engaged in autophagy-mediating pathways involving mechanistic target of Rapamycin (mTOR) as a key kinase promoting (cancer) cell growth." (PMID 34065956, 2021). "We have used the model to analyze the cancer cell cycle progression under various gene perturbations including Plk1-depletion conditions." (PMID 34887439, 2021). "Inhibition of PLK1, thereby interfering with multiple stages of mitosis, has been adopted as an anti-cancer strategy." (PMID 34093198, 2021).
cancer (continued). "While PLK1 inhibition has been well established to sensitize the cancer cells to radiation via mitotic regulation, EGFR is reported to be an arbitrator of DNA repair and is upregulated in ~ 50% of pulmonary carcinoma patients." (PMID 34138386, 2021). "In cancer cells, HSF1 is phosphorylated by polo-like kinase 1 (PLK1) at serine 216, causing it to sequester Cdc20." (PMID 34922589, 2021). "Extensive studies have shown that PLK1 overexpression is oncogenic in many types of cancer and it has been validated preclinically as a cancer therapeutic target." (PMID 35156101, 2021). "Its role in cancer includes cell differentiation and tumor progression, consequently resulting in poor clinical outcomes and therefore promoting the need for PLK1 inhibitors in cancer." (PMID 34063946, 2021). "This suggests the potential of NSC765600 and NSC765691 compounds to inhibit CCND1/CDK4/PLK1/CD44 expressions in cancer." (PMID 34063946, 2021). "PLK1 plays an important role in the initiation, maintenance and completion of mitosis, and it is the main driving force of cancer cell growth and proliferation." (PMID 33952716, 2021). "PLK1 promotes malignancy through diverse mechanisms and has gained increasing interest as a promising therapeutic target in many cancers including GBM." (PMID 34680264, 2021). "Studies have found that inhibiting the expression of PLK1 by interfering with multiple stages of mitosis can lead to tumor cell death, so PLK1 is expected to become a potential target for cancer treatment." (PMID 34696748, 2021). "This suggests the potential of NSC765600 and NSC765691 to inhibit CCND1/CDK4/PLK1/CD44 expressions in cancer." (PMID 34063946, 2021). "Searching for inhibitors of the PLK family kinases has been focused on PLK1 due to its well-established role in cancer as a tumor promotor." (PMID 33842469, 2021). "Since primary tumors from various tissues express elevated levels of PLK1, and this high‐level expression frequently correlates with a poor prognosis, PLK1 is a potential oncotarget for molecular cancer therapy and a prognostic marker." (PMID 34605140, 2021). "The authors then focused on PLK1, since it plays a key role in mitosis, and its activity is often deregulated in cancer cells and inhibitors against PLK1 have been developed as potential cancer therapeutics." (PMID 34065438, 2021). "It has been found that expression of both BIRC5 and Plk1 is out of control in cancer, and disruptions to survivin or PLK1 activity show many similarities, thus linking them in cell division and cell death." (PMID 33431968, 2021). "In cancer patients' tissues, PLK1/ARE‐regulated gene cluster was overexpressed in solid tumors and associated with poor survival." (PMID 33411958, 2021). "Despite these clinical trials using onvansertib, HNSCC is the cancer for which the inhibition of Plk1 is the most promising regarding our results." (PMID 34646387, 2021). "Cdc25, Cdc20, and Plk1 are well-known direct targets for inhibitors that are used to induce a cell cycle arrest in cancer cells and tumor regression." (PMID 34887439, 2021). "Paclitaxel, a microtubule-stabilizing agent, leads to mitotic arrest and upregulation of PLK1 due to interference with cell division in cancer cells." (PMID 34503223, 2021). "Among those is polo‐like kinase 1 (PLK1), which is overexpressed in cancer, leading to MAPK‐activated protein kinases 2 (MK2)‐dependent phosphorylation and inactivation of the mRNA decay‐promoting protein, tristetraprolin." (PMID 33411958, 2021).
cancer (continued). "Despite the indispensability of PLK1 in mutant KRAS‐driven cancer, efficacy of PLK1 inhibitors as monotherapy has been thwarted by poor response rates of patients." (PMID 34369083, 2021). "PLK1 expression has been commonly considered as a key player in cancer development capable of serving as a tumorigenic biomarker and poor-prognostic predictor." (PMID 34065956, 2021). "Paclitaxel, a microtubule-stabilizing agent, leads to mitotic arrest and upregulation of mitotic kinase PLK1 by interfering with cell division in cancer cells." (PMID 34503223, 2021). "We previously reported that hnRNPK regulates the proliferation of cancer cells by targeting polo-like kinase 1 (PLK1) and heme oxygenase-1 (HO-1)." (PMID 33731671, 2021). "For instance, Polo-like kinase 1 (PLK1) is overexpressed in several cancer subtypes, correlates with poor patient outcomes, and plays an important role in driving tumour cell growth." (PMID 33804165, 2021). "Our observations showed that, once inside the cancer cells, Artemisinin-mediated blockage of FoxM1 trans-activation results in downregulation of major transcriptional targets of FoxM1, such as Plk1, cyclinB1, Skp2 and Aurora B kinase." (PMID 34900697, 2021). "Polo‐like kinase 1 (Plk1) is involved in many aspects of the cell cycle, dysregulation of which is one common feature of cancer." (PMID 34051063, 2021). "Epithelium mesenchymal transition (EMT) is a key factor to control metastasis and polo-like-kinase 1 (PLK1 as mitotic kinase) regulates G2/M transition for over-expression in cancer metastasis." (PMID 34452179, 2021). "PLK1 and Aurora kinases are essential for proper mitotic progression, and those expressions are increased in proliferating cancer cells." (PMID 33465289, 2021). "The selective inhibitors of aurora A, as well as PLK1, are currently being evaluated in a number of clinical trials with various cancers, and detailed information on patient stratification is eagerly awaited." (PMID 34069817, 2021). "Due to the role of PLK1 in the cell-cycle and kinase pathway that are significant to cancer progression, PLK1 is recognized as a ‘druggable target’ for the development of therapeutics for the management of a variety of cancers." (PMID 33494392, 2021). "Drugs targeting mitotic kinases, especially aurora kinase A (aurora A) and polo-like kinase 1 (PLK1), have been extensively studied as cancer therapies." (PMID 34069817, 2021). "PLK1 has been found to be over-expressed in multiple cancers, including NSCLC, and the upregulated PLK1 is indicative of an unfavorable prognosis 2-4." (PMID 34522178, 2021). "Polo-like kinase 1 (Plk1) expression is inversely correlated with survival advantages in many cancers." (PMID 33547392, 2021). "In this study, we provide an example of a hypoxia-regulated oncogenic protein, Plk1, which significantly contributes to cancer metastasis and drug responses." (PMID 33547392, 2021). "PLK1 inhibitors have seen potentials in the clinical management of cancers by blocking cancer cell mitosis and triggering cell apoptosis." (PMID 33588776, 2021).
cancer (continued). "Together, our data strongly support a role for PLK1 in ZFP36/TTP‐regulated post‐transcriptional control that is compromised in cancer, and targeting this pathway can restore the aberrant activities." (PMID 33411958, 2021). "A pan-cancer mRNA sequencing data analysis correlates PLK1 expression levels with clinical parameter (patient overall survival) and reveals striking differentiated tumor-specific relations." (PMID 34065956, 2021). "Consistent with our findings, PLK1 inhibitors were shown to exhibit a synergistic effect with conventional chemotherapy drugs in various cancer types, suggesting the potential therapeutic value of PLK1 inhibitors to reverse chemoresistance in CRC treatment." (PMID 34881526, 2021). "Among PLKs, PLK1 is overexpressed in a wide range of human cancers, including leukemia, and is considered an attractive anticancer drug target." (PMID 33917995, 2021). "PLK1 is highly expressed in malignant tumors but scarcely detectable in normal tissues, and its expression correlates with poor patient survival." (PMID 34369083, 2021). "PLK1 has long been considered an effective target for anti-mitotic agents and has been the subject of an extensive effort for anti-cancer drug discovery." (PMID 32645997, 2020). "The combination of PLK1s role in CIN and its widespread overexpression across cancer types has led to the development and intensive study of PLK1 inhibitors as possible cancer therapeutics." (PMID 33066048, 2020). "Rigosertib was first described by Reddy and co-workers in 2005 as an in vitro inhibitor of polo-like kinase 1 (PLK1) and proposed to kill cancer cells through this activity, based on measurements of cell cycle progression and cellular PLK1 activity." (PMID 32619469, 2020). "The first assessment of inhibiting PLK1 as an anti-cancer strategy was done with anti-sense oligonucleotides in 2002." (PMID 33066048, 2020). "It is important to reliably identify effective therapeutic targets to improve treatments, but often, as in the case of PLK1, directly targeting a seemingly promising cancer-related molecule produces strong harmful side effects or unpredictable outcomes." (PMID 33066048, 2020). "PLK1 inhibitors, including volasertib, have been shown to arrest tumour cells in mitosis, with an increase in the polyploid cell population that lead cancer cells to mitotic death." (PMID 32792481, 2020). "The master mitotic regulator, Polo-like kinase 1 (Plk1), is an important gene cell division and a known cancer drug target." (PMID 33247393, 2020). "PLK1 itself is an attractive target for the development of cancer therapeutics because there is a mass of evidence indicating that it is highly overexpressed selectively in tumor cells compared to the healthy adult tissues." (PMID 33066048, 2020). "By using this method, the cancer cell proliferation and tumor growth were successfully inhibited by targeting the PLK‐1 gene (a marker of cancer gene)." (PMID 32328436, 2020). "Studies have indicated an oncogenic activity of overexpressed PLK1 in ovarian cancer, that is important for cancer cell progression and chemoresistance." (PMID 33257688, 2020). "The down-regulation of PLK1 is one of the potential mechanisms of the anti-cancer effect of dietary fiber-derived butyrate in CRC." (PMID 33537240, 2020).